PTGIS (prostaglandin I2 synthase)
Diseases named in the same sentence as PTGIS in open-access papers (continued):
Sharing a sentence is not in itself a finding about the gene and the disease.
tumor (34 papers, 2015 to 2025). "The potential relevance of this signaling pathway is underlined by the association between PTGIS expression in tumor tissue and progression-free survival (PFS) of HGSC patients (KM plotter database: logrank p = 0.00016, HR = 1.33)." (PMID 36551640, 2022). "Prostaglandin I2 synthase (PTGIS) was reported to promote the infiltration of tumor-associated macrophages (TAMs) and Tregs in TME, and high expression of PTGIS was associated with poor OS in multiple tumors." (PMID 34177903, 2021). "Our findings provide new ideas for elucidating the potential mechanism of PTGIS in tumor progression and the mechanism by which PTGIS is associated with tumor-infiltrating immune cells." (PMID 32463792, 2020). "Previous studies have provided possible explanations for why PTGIS expression in a tumor is associated with immune infiltration and poor prognosis." (PMID 32463792, 2020). "PTGIS, associated with poor OS in various cancers, may enhance tumor-associated macrophage infiltration and regulatory T cell (Treg) proliferation within the TME." (PMID 40426878, 2025). "Our findings indicated a significant increase in the expression of PTGDS and PTGIS, which indirectly suggests that the 1-cm area is associated with an increase in prostaglandin metabolites and may be at risk of promoting tumor progression." (PMID 38062443, 2023). "Importantly, our findings demonstrate that PTGIS can serve as an ideal diagnostic indicator and potentially acts as a tumor suppressor gene in EC." (PMID 37796199, 2023). "Prostacyclin, a metabolite produced by prostacyclin synthase (PTGIS), is historically believed to exert tumor-suppressive effects and lowers its level along with down-regulation of PTGIS associated with an aggressive tumor phenotype and a poor disease prognosis." (PMID 35453789, 2022). "Moreover, PTGIS expression was significantly positively correlated with infiltrating levels of macrophages and was strongly associated with a variety of immune markers, especially tumor-associated macrophages (TAMs) and T-regulatory cells (Tregs)." (PMID 32463792, 2020). "Compared to adjacent normal tissues, tumor tissues exhibited significantly reduced expression of PTGIS, DGKB, HSD17B13, INMT, and ACACB, while PLA2G10, GRHL1, LIPG, and PLA2G4F were markedly upregulated." (PMID 40426878, 2025). "ADIRF, tumor-associated genes CLU, FAM13C, as well as NGF, PRELP, RERG, PTGIS, GPC3 genes were among the top 20 overexpressed genes in EcE stromal cell population." (PMID 39169201, 2024). "Over-expressed HIF-1α then enters the nucleus, where HIF-1α methylates the HRE of the PTGIS gene, thereby preventing PTGIS transcription and tumor proliferation." (PMID 37475553, 2024). "The findings indicated that PTGIS expression was decreased in the >65 age group, tumor stage III–IV group, and lymph node (LN) metastasis group." (PMID 37796199, 2023). "Expression analysis revealed a down-regulation of PTGIS in EC as well as in several other tumor types." (PMID 37796199, 2023). "Prostaglandin I2 relative intensity and the expression of its related gene, PTGIS gene, are both decreased in tumor samples." (PMID 37256175, 2023). "Next, we used IHC to detect the protein expression of PTGIS and HRASLS in LUSC and paired tumor-adjacent normal lung tissues and found that the protein level of PTGIS was low in LUSC and HRASLS was high." (PMID 36703911, 2023). "PTGIS is highly expressed by cancer-associated fibroblasts (CAF), concomitant with elevated PGI2 synthesis, whereas tumor-associated macrophages (TAM) exhibit the highest expression of its surface receptor (PTGIR)." (PMID 36551640, 2022). "We chose primary tumor cells (ascTU) for this purpose, which express very low levels of PTGIS and PTGIR, so that autocrine effects are negligible." (PMID 36551640, 2022). "PTGIS is a HIF-1α target gene that plays a primary regulatory role in hypoxic tumor progression by activating the transcription of various oncogenes." (PMID 34512722, 2021).
tumor (continued). "As a novel oncogene, CIRBP has been shown to increase the expression of HIF-1α by binding to the 3′-UTR of its mRNA, which suppresses the expression of prostaglandin I synthase (PTGIS) and regulates tumor progression." (PMID 34490236, 2021). "In this study, our aim was to comprehensively analyze the relationship between the expression of PTGIS and prognosis in cancer patients and to explore the correlation between PTGIS and tumor-infiltrating immune cells." (PMID 32463792, 2020). "To explore the effects of PTGIS expression on tumor-infiltrating immune cells, we analyzed the relationships between PTGIS expression and various markers of immune cells in LUSC, OV, and STAD via public databases." (PMID 32463792, 2020). "PTGIS protein showed significantly reduced expression in OSCC (median: OSCC = 1.58 ng/μL vs. non-tumor = 2.80 ng/μL; p = 0.0156)." (PMID 30532780, 2018). "PTGIS has been reported to be a tumor suppressor in many kinds of cancers, our results displayed that PTGIS is downregulated both in BCa tissues and in BCa cell lines." (PMID 30315244, 2018). "Reduction of PTGIS expression can modulate its possible anti-tumor functions and contribute to carcinogenesis." (PMID 30532780, 2018). "The PGE2, PGI2, and LTB4 pathways have been linked with clinical progression through the PGE2 receptor PTGER3 on tumor cells, expression of the PGI2-synthesizing enzyme PTGIS by tumor cells and TAMs, as well as release of LTB4 into the TME by both cell types." (PMID 28275576, 2017). "The gene expression profile across all tumor samples and paired normal tissues were shown in, PTGIS was significantly upregulated in 1 out of all 33 cancer types compared with normal tissue, and it was significantly downregulated in 17 out of all 33 cancer types." (PMID 37779109, 2023). "The outcomes of the tumor formation experiment conducted in nude mice distinctly demonstrated that the overexpression of PTGIS yielded a notable suppression in tumor growth, as evidenced by a significant contrast between the PTGIS (+) group and the PTGIS (+)-NC group." (PMID 37796199, 2023). "Down-regulation of the PTGIS and PTGIR genes in eight different tumors may be associated with a more aggressive tumor phenotype due to the abolishment of prostacyclin’s tumor-suppressive effects." (PMID 35453789, 2022). "In addition, we initially explored the correlation between PTGIS and tumor-infiltrating immune cells by TIMER and Gene Expression Profiling Interactive Analysis (GEPIA)." (PMID 32463792, 2020). "Whether PTGIS is a pivotal factor that activates Tregs and tumor progression still needs further study." (PMID 32463792, 2020). "Thus, the correlation between PTGIS and tumor-infiltrating immune cells was assessed in different cancers with TIMER." (PMID 32463792, 2020). "Tumor tissue also expressed high levels of the histone deacetylase HDAC5 and the SUMO/ubiquitin E3 ligase TRIM28, which is linked to STAT3 signaling, as well as low expression of the tumor suppressor PTGIS." (PMID 30645971, 2019). "Similarly, to explore the tumor biological functions of PTGIS in BCa, a PTGIS expression plasmid was constructed, and the overexpression efficiency was verified by Western blot." (PMID 30315244, 2018). "Genes related to the “METABOLISM OF LIPIDS” pathway are PTGIS and HRASLS, and they are also related to tumor immunity." (PMID 39411374, 2024). "From the results of the immune infiltration, we can find that the PTGIS gene is positively correlated with mast cell-activated macrophages M2 and macrophages M0 in COAD, which can promote the development of a tumor." (PMID 37779109, 2023). "Our study suggested that PTGIS and HRASLS played an important role in LUSC phenotype, prognosis, and tumor immunity." (PMID 36703911, 2023). "PTGIS and HRASLS can be used as new therapeutic targets for LUSC as well as biomarkers for prognosis and tumor immunity, which has positive significance for guiding the immunotherapy of LUSC." (PMID 36703911, 2023).
tumor (continued). "In vitro, we found that PTGIS was a tumor-promoting gene of LUSC and HRASLS was a tumor-suppressor gene." (PMID 36703911, 2023). "WGCNA found that 28 genes including CD4 and IL10RA were related to the expression of PTGIS/HRASLS and tumor immune infiltration." (PMID 36703911, 2023). "Consistent with sequencing studies, we identified expression of PTGIS and PTGES in both αSMA + fibroblasts and in tumor cells." (PMID 36277993, 2022). "The results indicated that AIFM3, HSH2D, and PTPN6 were significantly up-regulated, while DCHS1, PTGIS, FLRT2, PCSK5, and CLSTN2 were significantly down-regulated in tumor samples compared with normal samples." (PMID 34512722, 2021). "Some new tumor-specific markers for different pathologic types of RCC, such as SPOCK1, PTGIS, REG1A, CP and SPAG4 were identified and validated." (PMID 34722263, 2021). "IHC results showed that ALOX12B and PTGIS proteins presented low expression in groups of OSCC and non-tumor tissues." (PMID 30532780, 2018). "In addition, we proved that PTGIS overexpression could suppress the BCa cells proliferation and migration, together with our demonstration that PTGIS increased the protein level of PPAR-γ and suppressed EMT, we demonstrated that PTGIS also acts as a tumor suppressor in BCa." (PMID 30315244, 2018). "Previous study has confirmed stromal cells can induce the increased expression of PTGIS and PGI2, which may lead to tumor cell growth and unfavorable outcomes." (PMID 39060344, 2024). "PTGIS and PLAAT1 might serve as new therapeutic targets for LUSC as well as biomarkers for prognosis and tumor immunity." (PMID 38363409, 2024). "Therefore, our study suggests that PTGIS and HRASLS have potential clinical value in guiding immunotherapy as novel therapeutic targets for LUSC as well as biomarkers for prognosis and tumor immunity." (PMID 36703911, 2023). "We identified LMRGs PTGIS and HRASLS that were related to the prognosis and tumor immunity of LUSC." (PMID 36703911, 2023). "Tumor cells express synthases TBXAS1 (TXA2, TXB2, 12-HHTre) and CYP2S1 (12-HHTre), and some subclusters are enriched for PGE2 synthase PTGES or prostacyclin synthase PTGIS." (PMID 36277993, 2022). "Thus, the results identified some new tumor-specific markers and verified SPOCK1, PTGIS, REG1A, CP and SPAG4 in different types of RCC." (PMID 34722263, 2021). "In addition, three tumor-specific genes, namely, SPOCK1, PTGIS and NDUFA4L2, were verified using IHC-P in type 2 pRCC tissues (–D) and compared with the negative controls in normal kidney tissues (–C)." (PMID 34722263, 2021). "TIMER and GEPIA have most of the common transcriptomics data derived from the TCGA database, so we selected the types of cancer in TIMER in which PTGIS had a significantly negative correlation with tumor purity and prognostic significance in GEPIA." (PMID 32463792, 2020). "The PTGIS expression level had a significant negative correlation with tumor purity but significant positive correlations with the levels of 6 infiltrating immune cells in LUSC." (PMID 32463792, 2020). "We observed that PTGIS expression levels were significantly associated with tumor purity in 26 kinds of cancer, of which 23 kinds of cancer showed a negative correlation between PTGIS expression and tumor purity." (PMID 32463792, 2020). "Differential analysis of tumor versus healthy biopsies highlighted 166 candidate genes with different DNA methylation levels in their promoters, which included the tumor-specific hypomethylated EGFL8 promoter as well as hypermethylated promoters of ESR1, PTGIS, and GATA3." (PMID 30645971, 2019). "Furthermore, the PTGIS gene in READ was positively correlated with macrophage M2 and macrophage M0, which could promote tumor development." (PMID 37779109, 2023).
tumor (continued). "Interestingly, PTGIS expression also has a positive correlation with TIM-3, an important gene mediating T cell exhaustion and macrophage activation; the presence of the exhausted phenotype downregulates the immune response in tumor-bearing hosts." (PMID 32463792, 2020). "Furthermore, the authors suggested that the effect of PTGIS was related to its ability to promote vascularization; also, PTGIS gene and protein expression were shown to be reduced in HNSCC samples compared to non-tumor mucosa." (PMID 30532780, 2018). "Many studies have reported that PTGIS acted as a tumor suppressor in several cancers, our microarray analysis (GEO accession No. GSE76211) revealed that PTGIS is significantly downregulated in BCa tissues, and qRT-PCR analysis results proved this conclusion." (PMID 30315244, 2018). "The opposite trend was observed with PTGER4, PTGDS, PTGER3, PTGIS, PTGFR, and PTGS1 genes, which showed overexpression in the adjacent non-tumor tissue, followed by downregulation in the tumor." (PMID 26207152, 2015).
cancer (19 papers, 2015 to 2025). A tumor composed of atypical neoplastic, often pleomorphic cells that invade other tissues. "In our study, we observed that the PTGIS expression level was associated with the prognosis of various cancers." (PMID 32463792, 2020). "Even though anti-tumorigenic functions and a favorable clinical outcome have been linked to PGI2 in several cancers, increased intra-tumoral PTGIS expression derived from stroma cells is associated with poor clinical outcome in HGSC suggesting an entity-specific role for PTGIS and its product PGI2." (PMID 36551640, 2022). "Studies have shown that the PTGIS enzyme is associated with the progression of cancer." (PMID 30532780, 2018). "PTGIS plays a positive role in cardiovascular diseases by regulating fatty acid metabolism, while it is the opposite in cancer." (PMID 36785673, 2023). "The differential expression of PTGIS gene in different cancer types and normal tissues was analyzed in Oncomine database." (PMID 37779109, 2023). "Across various cancer types, significantly more datasets showed low expression of PTGIS in cancer samples versus normal samples than overexpression of PTGIS." (PMID 32463792, 2020). "Next, we further examined PTGIS expression in multiple human cancers with RNA-seq data from The Cancer Genome Atlas (TCGA)." (PMID 32463792, 2020). "In our research, PTGIS mRNA expression profiles and prognosis were analyzed with datasets from multiple kinds of cancer from Oncomine and TCGA." (PMID 32463792, 2020). "A total of 33 cancer types were included in the analysis of the relationship between PTGIS expression and survival." (PMID 32463792, 2020). "In the comparison of various cancers with normal tissues, we observed differences in PTGIS expression." (PMID 32463792, 2020). "To explore the correlation between PTGIS expression and prognosis in human cancers, we investigated the effects of PTGIS expression on survival via PrognoScan." (PMID 32463792, 2020). "Previous studies have shown that the expression of PTGIS is induced by hypoxic conditions in human lung fibroblast cells and cancer cell lines, and can activate vascular endothelial growth factor." (PMID 28448578, 2017). "Cell experiments showed that PTGIS was expressed at a lower level in cancer." (PMID 37779109, 2023). "Furthermore, in pan-cancer analysis, it was consistently observed that PTGIS was down-regulated in most tumors." (PMID 37796199, 2023). "Furthermore, the findings derived from both in vitro and in vivo experiments offered supplementary substantiation, affirming the involvement of PTGIS in impeding the advancement of cancer within the scope of EC." (PMID 37796199, 2023). "In order to construct PPI networks and functional annotations, we ran a STRING database, and the KEGG results showed that a network of PTGIS pathways, mainly involved in metabolic pathways, arachidonic acid metabolism, steroid biosynthesis, cancer pathways, etc.." (PMID 37779109, 2023). "Therefore, it shows that the PTGIS gene can promote the occurrence of cancer in COAD." (PMID 37779109, 2023). "Therefore, this shows that the PTGIS gene can promote the occurrence of cancer in READ." (PMID 37779109, 2023). "Among these model genes (FLNC, KLK6, PTGIS, PLAAT1 and GLYATL2), FLNC is an actin-binding protein that regulates the actin cytoskeleton in cells and is involved in cancer metastasis." (PMID 38363409, 2024). "This revealed up to 12 genes that are suppressed in CRC, including genes that had been previously found misregulated in cancer, such as HPGD, PTGIS, PTGER3, and AKR1B1." (PMID 26207152, 2015). "Furthermore, we demonstrated that PTGIS is a HIF-1α targeted gene, a major regulator in hypoxic cancer progression by activating transcription of various oncogenes." (PMID 30315244, 2018).
cancer (continued). "Even though the altered expression of many genes is maintained or even exacerbated in tumors, a subset overturns its deregulation, reversing the expression levels in the cancer tissue to either upregulation (i.e., PTGES3) or a strong downregulation (i.e., PTGIS)." (PMID 26207152, 2015). "In addition, PTGIS expression was significantly correlated with infiltrating immune cells, including B cells, CD4+/CD8+ T cells, macrophages, neutrophils, and dendritic cells, in various types of cancers." (PMID 32463792, 2020). "However, the mechanism of the PTGIS gene on cancer is not very clear." (PMID 37779109, 2023).
cardiovascular diseases (5 papers, 2017 to 2025). "The clear and definite function of upregulated PTGIS is protecting patients with cardiovascular diseases, such as pulmonary hypertension, heart failure, and hyperlipidemia." (PMID 36785673, 2023).
infection (1 paper, 2021). The state of being infected such as from the introduction of a foreign agent such as serum, vaccine, antigenic substance or organism. "The eGFP signal in the liver transfected with the PTGIS overexpression plasmid indicated a successful infection of the virus." (PMID 34112940, 2021).
pancreas (1 paper, 2015). "Indeed, not only colorectal, but also liver, stomach, and pancreas tumors present high rates of hypermethylation of PTGIS, AKR1B1, PTGER3, and PTGFR." (PMID 26207152, 2015).
PTGIS also shares sentences with these, for which no sentence is quoted: diabetes (4 papers); endothelial dysfunction (3); heart failure (3); lung squamous cell carcinoma (3); myocardial infarction (3); renal disorder (3); endometrial cancer (2); leukemia (2); Oral Squamous Cell Carcinoma (2); ovarian serous cystadenocarcinoma (2); acute kidney injury (1); adenocarcinoma (1); adenoma (1); adrenocortical carcinoma (1); aneurysm (1); breast tumors (1); cervical cancer (1); childhood-onset schizophrenia (1); cholestasis (1); colon polyps (1); Crohn disease (1); dysplasia (1); endotoxemia (1); essential hypertension (1); glioblastoma multiforme (1); glomerular disease (1); haemorrhage (1); head and neck squamous cell carcinoma (1); hypothyroidism (1); Insulin resistance (1).
A further 17 diseases each share a sentence with PTGIS in 1 paper.